MB21D2 (Mab-21 domain containing 2)
Description:
Probable nucleotidyltransferase that catalyzes the formation of cyclic dinucleotide second messenger in response to some unknown stimulus.
Synonyms: hMB21D2; C3orf59; D2A
Tractability: PROTAC: its protein half-life has been measured.
Gene: Protein-coding gene on chromosome 3 (192,796,815 to 192,917,856, reverse strand). Ensembl gene ENSG00000180611.
Subcellular location (Human Protein Atlas): Cytosol
Gene Ontology:
Molecular function: cadherin binding; protein binding; protein-containing complex binding
Genetic constraint (gnomAD): Loss-of-function variants: 9 observed, 34.04 expected, observed/expected ratio (o/e) 0.26, 90% interval 0.16 to 0.46. The upper end of that interval is the gene's LOEUF score, 0.46, which puts it in group 2 of 6, group 1 being the genes least tolerant of losing a copy. Missense variants: 540 observed, 655.26 expected, observed/expected ratio (o/e) 0.82, 90% interval 0.77 to 0.88. Synonymous variants: 241 observed, 250.61 expected, observed/expected ratio (o/e) 0.96, 90% interval 0.87 to 1.07.
Homologues: Orthologues: chimpanzee MB21D2 (99% identical), pig MB21D2 (99% identical), dog MB21D2 (99% identical), guinea pig MB21D2 (99% identical), macaque MB21D2 (99% identical), mouse Mb21d2 (99% identical), rat Mb21d2 (98% identical), tropical clawed frog mb21d2 (95% identical), rabbit MB21D2 (85% identical), zebrafish MB21D2 (85% identical), zebrafish mb21d2 (79% identical), Drosophila melanogaster CG15865 (25% identical). Paralogues in human: TMEM102 (30% identical), ITPRIPL2 (16% identical), CGAS (14% identical), ITPRIP (13% identical), ITPRIPL1 (11% identical), MAB21L4 (11% identical), MAB21L1 (11% identical), MAB21L2 (11% identical), MAB21L3 (11% identical).
Diseases named in the same sentence as MB21D2 in open-access papers:
MB21D2 is named in the same sentence as 8 diseases in open-access papers, as found by Europe PMC text mining. Sharing a sentence is not in itself a finding about the gene and the disease. The quoted sentences say what the papers report.
bladder cancer (1 paper, 2025). "The remaining four genes, CRTC1, MB21D2, USP44 and FGFR2, may drive bladder cancer through other mechanisms of pathway crosstalk, which requires further investigation." (PMID 40768543, 2025).
head and neck cancer (1 paper, 2022). A primary or metastatic malignant neoplasm affecting the head and neck. "Overexpressed MB21D2 reportedly promotes a pro-oncogenic progression of head and neck cancer, and it also induces less sensitivity toward DNA-damaging agents, such as RT." (PMID 35453806, 2022).
head and neck squamous cell carcinoma (1 paper, 2020). A squamous cell carcinoma that arises from any of the following anatomic sites: lip and oral cavity, nasal cavity, paranasal sinuses, pharynx, larynx, and salivary glands. "In this study, we investigated the oncogenic roles of a novel gene named MB21D2 which harbors a recurrent Q311E mutation which is overexpressed in head and neck squamous cell carcinoma (HNSCC)." (PMID 32979859, 2020).
multiple myeloma (1 paper, 2020). "The predicted interaction of MB21D2 with Mab21‐nucleotidyltransferase enzymes, such as cGAS, and mitochondrial regulator, such as MIEF proteins, may further explain the clonal selection event, as fittest clone selection was previously observed in many cancers such as multiple myeloma." (PMID 32979859, 2020).
cancer (3 papers, 2020 to 2022). A tumor composed of atypical neoplastic, often pleomorphic cells that invade other tissues. "In addition, (phospho)proteomics study confirms that many cytoskeleton-associated proteins, e.g., β-catenin, PIK3CA, and MB21D2, are important signaling mediators, further suggesting their biofunctional roles in cancer development." (PMID 36551290, 2022). "Interestingly, these proteins, in addition to other identified HDAC3 targets including MB21D2 and the melanoma-associated antigen MAGED1, also have cancer-associated functions." (PMID 35994477, 2022). "MB21D2 is overexpressed in various cancer types, including HNSCC, LUSC, ESCA, and CESC." (PMID 32979859, 2020).
tumor (3 papers, 2022 to 2025). "Our study provides compelling evidence that MB21D2 acts as a tumor suppressor in ESCC by negatively regulating the Wnt/β-catenin signaling pathway." (PMID 40657359, 2025). "MB21D2, a key enzyme involved in the cGAS/STING signaling pathway, is also frequently mutated in NSCLC and HNSCC to promote tumor progression." (PMID 35991889, 2022). "Additionally, five key genes (SYT16, NCEH1, NXPE3, MB21D2, and DZIP1L) were identified, which simultaneously appeared in A→B compartment switching, TADs, and chromatin loops in tumor samples, with four of these genes located on the q arm of chromosome 3." (PMID 41049290, 2025).
MB21D2 also shares sentences with these, for which no sentence is quoted: hepatoid adenocarcinoma (1 paper); leiomyoma (1).